MMP9 (matrix metallopeptidase 9)
Diseases named in the same sentence as MMP9 in open-access papers (continued):
Sharing a sentence is not in itself a finding about the gene and the disease.
cancer (continued). "Moreover, the docking energy of BPU computationally scored − 9.0 kcal/mol with the human matrix metalloproteinase 2 (MMP-2) and − 7.8 kcal/mol with the human matrix metalloproteinase 9 (MMP-9), denoting promising binding results as compared to the existing drugs for cancer therapy." (PMID 38129413, 2023). "Therefore, we studied whether MMP9, MMP12, FABP4, and CD36 genes are correlated with poor prognosis in various cancers." (PMID 37978381, 2023). "The change in the expression of MMP2 and MMP9 concerned only cancer cells and no other cells." (PMID 37509417, 2023). "Next, we investigated MMP-9 gene expressions and observed that mRNA levels of MMP-9 were also significantly upregulated under dynamic conditions (*p < 0.05) compared to static conditions in the absence of bone, indicating the effect of fluid shear stress on cancer cell migration." (PMID 36863017, 2023). "As matrix metalloproteinases (MMPs) mediate cancer cell invasion and metastasis in human malignancies, including OC38, in this study we aimed to explore whether irisin affects the mRNA expression level of MMP2 and MMP9 as two verified metastasis markers in OC." (PMID 36599894, 2023). "Treatment of NK-92 cells with an MMP9-blocker enhanced surface expression of NKG2D and secretion of perforin and granzyme B by these cells, suggesting that MMP9 inhibition can reverse the cancer cell-induced immunosuppressive effect and potentiate NK cell effector function." (PMID 37488598, 2023). "Therefore, cellular function, migration, and invasion of cancer cells and EMT may be regulated by MMP9 and MMP2, and the expressions of upstream regulators such as AMPK, NF-κB, and TIMPs need to be further explored." (PMID 35770085, 2022). "Their differentiation is stimulated by chemotactic factors secreted by cancer cells to promote tumor progression such as proliferation induction, ECM remodeling, angiogenesis, and adaptive immune evasion, either by the release of EGF, or by the degradation of ECM proteins (MMP2 and MMP9)." (PMID 35205204, 2022). "Additionally, noradrenaline augmented levels correlated with high levels of MMP-9 (rs = 0.332) in the control group but not in cancer patients." (PMID 36213817, 2022). "IL-17 has been found to promote migration, extracellular matrix degradation, and invasion of cancer cells, including GBM cells, through the activation of PI3K–AKT and STAT3 signaling, as well as through the elevation of expression of the matrix metalloproteinases MMP-2 and MMP-9." (PMID 35884700, 2022). "Exosomes from cancer stem cells could enhance the proliferative, migratory, and/or invasive abilities of fibroblasts, accompanied by the upregulated expression of MMP-2 and MMP-9." (PMID 36230852, 2022). "Without MMP9, TCs lost the function of promoting cancer cell migration and invasion." (PMID 34376644, 2021). "At least, in other cancers, in lung adenocarcinoma (LUAD), a comprehensive proteogenomic characterization of the tumors in comparison to matched normal adjacent tissues showed that, besides other molecules, MMP-8, MMP-9 and MMP-12 are correlated with rich macrophage infiltration." (PMID 34204372, 2021). "Additionally, the same research group analyzed whether there was a correlation between Nucb2-regulated cell migration and the significance of Nucb2 in the migration of cancer cells facilitated by the action of matrix metalloproteases MMP-2 and MMP-9." (PMID 34073612, 2021). "Moreover, coculturing basal-like cancer cells with fibroblasts induced the expression of various interleukins and chemokines such as IL-6, IL-8, CXCL1, and CXCL3 and enhance metastasis through upregulating matrix metalloproteinase-9 (MMP-9)." (PMID 33916931, 2021). "In addition, CTP/CDDP could block HIF-1α/MMP9 pathway and promote RKIP expression in hypoxic cancer cells, thus inhibiting the EMT process and enhancing the anti-metastatic efficacy." (PMID 34399762, 2021).
cancer (continued). "Unfortunately, this compound showed no-inhibition toward both MMP9 or 4T1 and thus, the activity of both IC n-hexane and ethylacetate partitions toward MMP9 and cancer cells was not due to the presence of DOP, but rather of other compounds that to date, we have not successfully isolated." (PMID 33800366, 2021). "In non-transfected cancer cells, we also observed that CP did not reduce the level of MMP-9." (PMID 34884588, 2021). "This study showed the anti-cancer effect of desflurane but not sevoflurane via MMP9/miR-335." (PMID 33919449, 2021). "In that context, an elevated MMP-9 mRNA in mesenchymal cells of CR patients, correlating with a decrease in E-cadherin expression was reported by us previously, consistent with the role of MMP-9 in epithelial-mesenchymal transition (EMT) in platinum resistant ovarian and other cancers." (PMID 35047406, 2021). "We could not measure MMP-9 in cancer cell lines as it seemed that MMP-9 was too low to be detected in these cell lines." (PMID 33086573, 2020). "Fucoidan derived from U. pinnatifida sporophylls inhibit hypoxia in cancer cells through nuclear translocation, activity of HIF-1α and reduction in the levels of phosphorylated-PI3K (p-PI3K), p-Akt, p-mTOR, p-ERK, NF-κB, MMP-2, and MMP-9, but increased TIMP-1 levels." (PMID 32354032, 2020). "They found that EEOS inhibited cancer invasion and MMP-9 activity, but not that of MMP-2." (PMID 32102512, 2020). "Remodelling of extracellular matrix play particularly important role in creating microenvironment permissive for metastatic cancer cells: activation of fibroblasts/myofibroblasts, reorganization of collagen fibers, and change in expression of ECM-remodelling enzymes such as MMP2, MMP9 and LOX43,45." (PMID 32286443, 2020). "Finally, we identified a subset of EMT markers regulated by PRMT5 in MM, including E‐cadherin, N‐cadherin, α‐smooth muscle actin and MMP9, indicating that targeting PRMT5 could hamper this crucial process for cancer progression." (PMID 32301278, 2020). "However, the protein levels of MMP9, MMP12 and TIMP3 are increased in cancer cells." (PMID 32171282, 2020). "Furthermore, sodium danshensu treatment decreased MMP-2 expression without altering MMP-9 expression in both these cancer cells." (PMID 33101201, 2020). "Although this ligand may be useful for imaging MMP9 expressing cancers, the lack of MMP9 specificity of the ligand could result in low signal-to-noise ratio, as MMP2 presence in normal tissues is more widespread compared to MMP9." (PMID 33007872, 2020). "Thus, down-regulation of either MMP9 or VEGFA expressions could further suppress the metastatic potential and angiogenic of cancer cells." (PMID 30728391, 2019). "In our experiments, we confirmed that the protein expression of VEGF, MMP-2, MMP-7 and MMP-9 in mouse GC tissue was significantly increased after activation of ADRB signalling under the condition of chronic stress; thus, these proteins play a role in promoting cancer and metastasis." (PMID 31624248, 2019). "Secondly, metalloprotease and adhesion molecules, MMP9 and ADAM23, are involved in the breakdown of the extracellular matrix in physiological processes such as embryonic development, reproduction, and tissue remodeling; they also play an important role in metastasis of cancer." (PMID 31921385, 2019). "Furthermore, cancer metastasis-indicators MMP2 and MMP9 proteins were down-regulated." (PMID 32083017, 2019). "Furthermore, we observed that both the mRNA and protein levels of a collection of NF‐κB downstream effectors that are central co‐ordinators of cancer cell metastasis, such as ICAM1, VCAM1 and MMP9, were decreased by RPS15A knockdown, but increased by RPS15A overexpression." (PMID 30661291, 2019).
cancer (continued). "Our findings identified unappreciated roles of monocyte‐derived MMP9 to create a permeable EC monolayer, and further revealed that macrophages generated microtracks to allow extravasated cancer cells to sustain high invasiveness regardless of intrinsic metastatic potential." (PMID 31179226, 2019). "Therefore, MMP-9 and MMP-2 could be CoQ0-responsive mediators whose ECM degradation could result in ensuing cancer invasion and migration." (PMID 31068208, 2019). "Additionally, elevation of miR-149 restrained the expression of MMP-9 and MMP-2 in cancer cells." (PMID 30126849, 2018). "EVs carry molecules such as CD24, and epithelial cell adhesion molecule (EPCAM1), which directly regulate cancer-cell migration, proteases (MMP2, MMP9), which promote ECM degradation and cancer invasiveness, or EV-associated mRNAs, such as miR21, which may induce resistance to paclitaxel." (PMID 30200478, 2018). "Moreover, Tan IIA inhibited NF-κB signalling and expression of MMP-2 and MMP-9, and increased levels of tissue inhibitor of matrix metalloproteinases type 1 and 2 (TIMP-1 and TIMP-2), therefore suppressed invasion and metastasis of cancer cells." (PMID 30373594, 2018). "Therefore, the present study, examined the specific mechanisms by which BITC, PEITC, SFN, and N-methyl phenethylamine (NMPEA), a PEITC analog lacking an isothiocyanate functional group, downregulate MMP-9 expression in various cancer cells." (PMID 28969043, 2017). "The inhibitory effects of isothiocyanates on MMP-9 and cell migration were also apparent in MDA-MB-231 and SW480 cells, suggesting that the ability of isothiocyanates to inhibit migration is dependent on the sulfur-containing functional group, rather on the cancer cell line itself." (PMID 28969043, 2017). "No expression of MMP9 was observed in normal samples and only four cancers expressed this gene." (PMID 29137669, 2017). "However, how Rab40b regulates targeted MMP2 and MMP9 secretion and localized ECM remodeling remains to be understood, and the machinery that regulates levels of Rab40b in cancer cells is also unknown." (PMID 27789576, 2016). "However, the increased levels of MMP-9 have been described in several pathologic conditions and/or inflammatory status suggesting that it is not clearly specific in cancer." (PMID 27115178, 2016). "The mechanisms mediating S100A8 and S100A9 regulation of MMP2 and MMP9 expression in cancer cells are not yet known but may involve their calcium-binding activity." (PMID 27086923, 2016). "PTK7 and MMP-9 are enriched at pericellular region of cancer cells but not around normal cells." (PMID 27689325, 2016). "Moreover, we also determined that BX357664 could suppress the expression of MMP2 and MMP9 in RCC cells (p < 0.05), providing more evidence for the inhibitory role of BX357664 in cancer metastasis in RCC." (PMID 27806310, 2016). "Among MMPs, MMP-2 (gelatinase A) and MMP-9 (gelatinase B) are vital enzymes involved in the degradation of gelatin, collagen and laminin, main components of ECM and high expressions of them are indicators of high invasive potential of cancer cells and are related to poor prognosis of patients." (PMID 27144433, 2016). "To check whether PARP-1 has any role in the regulation of metastatic nature of cancer cells after treatment with carbon ion exposure, we looked into the activities and expression of two major matrix metalloproteinases, MMP-2 and MMP-9, which are highly activated during cancer metastasis." (PMID 27659937, 2016). "Hence, suppressive effects of calcipotriol on the expression of MMP-9 and MMP-13 could be considered as a strategy for cancer treatment." (PMID 27271600, 2016). "Basigin-2, also known as CD147, is a transmembrane glycoprotein present on the cancer cell surface belonging to the immunoglobulin superfamily, which was found to induce expression of matrix metalloproteinases (MMPs), particular MMP-2 and MMP-9 in fibroblasts or tumor cells." (PMID 27042161, 2016).
cancer (continued). "Therefore, the expressed MMP9 and MMP13 are able to regulate the metastasis of cancer cells." (PMID 25866480, 2015). "In addition to cytokines, also MMP-9 production and TF activity were higher in DVT+ cancer patients than in those DVT- and in healthy controls (mean ± SD, 103 ± 23, 73 ± 24, 8.8 ± 4, for MMP-9 and mean ± SD, 35.6 ± 6.4, 28 ± 5, 3.3 ± 0.7 for TF activity, respectively)." (PMID 26192925, 2015). "Because MMP-2 and MMP-9, as well as MMP-7, are known to be the downstream targets of β-catenin, significant inhibition in the level of β-catenin by embelin may inhibit MMP-2 activity and cancer cell migration." (PMID 26252009, 2015). "Moreover, expression of the matrix metalloproteinases coded by the MMP2, MMP9, and MMP14 genes confers these cells the ability to degrade extracellular matrix proteins, an important step in various stages of cancer progression, including angiogenesis, invasiveness, and metastasis." (PMID 26110651, 2015). "Our results show that PMS can inhibit the growth of cancer cells without side effect on normal cells, as well as their ability of invasion and metastasis, while reducing the MMP9 and MMP2 activity." (PMID 26674531, 2015). "We found that MMP-2 decreased by inhibiting CD44 via blocking mTOR signaling, whereas MMP-9 was not, demonstrating that the MMPs may have diverse roles in the signaling pathways of various cancers." (PMID 26202311, 2015). "In contrast, MMP-9 has very limited or no expression in these cancer cells." (PMID 24586907, 2014). "Interestingly, we also observed that DLK1 could still moderately upregulate MMP9 expression when the Notch signaling pathway was blocked, implying that DLK1 may function in cancer invasion in both Notch signaling-dependent and -independent manners." (PMID 24621612, 2014). "Meanwhile, MMP-9 and TIMP-2 could also affect the progression of cancer." (PMID 24829764, 2014). "Matrix metalloproteinase-2 (MMP-2) and matrix metalloproteinase-9 (MMP-9) are highly expressed in various malignant tumors and are involved in the degradation and breakdown of the environmental extracellular matrix (ECM) and the basement membrane, promoting cancer metastasis." (PMID 25222667, 2014). "In addition, it resulted in a significant reduction of α5 and β1 integrin protein and urokinase and matrix metalloproteinase 9 (MMP9) activity, and subsequently leading to a reduction of adhesion of cancer cells to human mesothelial cells that cover the peritoneum mainly via reduction of integrin." (PMID 23320251, 2012). "Expression of MMP-9 in different renal tissues between patients with and without cancer." (PMID 23110201, 2012). "In fact, it was shown in mice lacking MMP-9 that this gene is functionally involved in the regulation of oncogene-induced keratinocyte hyperproliferation, progression to invasive cancer, and end-stage malignant grade epithelial carcinomas." (PMID 22776414, 2012). "Moreover, the downregulation of MMP-9 and MMP-2 by these flavonoids is due to the interference with the transcription factor AP-1 there by suggesting these flavonoid glycosides as potent natural chemopreventive agents for cancer." (PMID 21197102, 2010). "In recent years, the p38 MAPK has emerged as a key signaling molecule in the regulation of cancer invasion and metastasis by modulating the expression and activity of molecules governing the degradation of extracellular matrix (that is, urokinase plasminogen activator, MMP-2, and MMP-9)." (PMID 21167057, 2010). "Therefore, we suggest that berberine may be used as an effective ingredient for anti-cancer products, which can prevent cancer metastasis and the degradation of ECM proteins by MMP-9." (PMID 19052522, 2008). "In the present study, MMP-9 was not intensely expressed, probably because in this type of T/NK cell extranodal lymphoma lack of participation of the adequate stromal elements such as fibroblasts, which are more evident in carcinomas." (PMID 18954439, 2008).
cancer (continued). "Moreover, MMP-9 was not expressed in cancer cells, either, but in myeloid cells." (PMID 40075643, 2025). "Furthermore, bioinformatic analysis of miR‐34a targets in various cancers identifies numerous target genes such as Jagged 1 (JAG1), CD44, SRY (sex determining region Y)‐box 4 (SOX4), Notch homolog 2 (NOTCH2), Matrix metallopeptidase 9 (MMP9), Interleukin 6 (IL‐6), and SMAD family member 4 (SMAD4)." (PMID 40336533, 2025). "Some of the key participants in the growth and aggressiveness of cancer cells of glycolytic enzymes could be lactate dehydrogenase (LDH), caspases, cyclin-dependent kinases, redox–detox enzymes, matrix metalloproteinases-2/9 (MMP-2 and MMP-9), and NAD+-dependent enzymes." (PMID 38672151, 2024). "Furthermore, by secreting VEGF, Bv8, MMP-9, and basic fibroblast growth factor (b-FGF), MDSCs play an important role in TME reorganization, cancer angiogenesis, metastasis, and the formation of pre-metastatic niches, hence regulating cancer initiation and progression." (PMID 39609700, 2024). "Besides MMP9, FOXM1 (Forkhead Box M1) was a component of GO BP categories “negative regulation of the apoptotic process”, “positive regulation of cell proliferation”, and KEGG pathways “transcriptional misregulations in cancer”, and “pathways in cancer”, as well as major upregulated hub gene." (PMID 37373974, 2023). "Notably, we found that MMP9 expression in stromal cells did not correlate with clinicopathologic parameters or patient survivals, despite previous evidence suggesting that MMP9 derived from cancer stroma contributes to cancer progression." (PMID 37296952, 2023). "In addition, AKT may be connected with cancer proliferation and apoptosis in epithelial ovarian tumour cells, possibly because of the involvement of AKT in the regulation of downstream signalling molecules, including CyclinD1, Bcl2, PCNA and MMP9." (PMID 37056382, 2023). "Furthermore, MMPs, including MMP9 and MMP14, may confer resistance to various cancer therapies by altering tumor vasculature to impact drug delivery, promoting survival pathways in cancer cells, or driving the acquisition of more aggressive phenotypes through EMT." (PMID 37760801, 2023). "Notably, MMP9 expression in cancer stromal cells did not relate to poor clinical features." (PMID 37296952, 2023). "However, it is not clear whether MMP-9 produced by host with C. albicans infection plays a role in promoting or inhibiting cancer formation." (PMID 36246294, 2022). "BMP-7 and MMP-9 expression in DU 145 and MDA-MB-231 cells were investigated at early and late time points by Western blot analyses in order to determine whether ESE-16 in combination with 4 Gy radiation affects the invasive and migratory signaling properties in cancer cells." (PMID 34440874, 2021). "Furthermore, the downregulation of the intrinsically higher levels of MMP2 and MMP9 by COL1 in resistant W1CR cells confirm the discrete regulation of both resistance pathways and offer interesting new targets for clinical sensitization strategies in the treatment of cancer patients." (PMID 33287446, 2020). "Interleukin (IL)-6 drives many of the cancer ‘hallmarks’ through downstream activation of the Janus kinase/signal transducer and activator of transcription 3 (JAK/STAT3) signaling pathway, we wanted to find whether STAT3 plays a role in IL-6-induced MMP2 and MMP9 expression." (PMID 31409371, 2019). "Besides, qRT‐PCR and immunohistochemistry assays were performed to evaluate the expression of VEGF, MMP‐2, and MMP‐9 related to the invasion and metastasis of cancer, and the results showed that Sanhuang decoction could significantly inhibited the expression of VEGF, MMP‐2, and MMP‐9." (PMID 31762993, 2019).